RNU6-77P (RNA, U6 small nuclear 77, pseudogene)
Synonyms: RNU6-77
Gene: Small nuclear RNA gene on chromosome 13 (81,265,747 to 81,265,837, forward strand). Ensembl gene ENSG00000222486.
Homologues: Orthologues: chimpanzee U6 (98% identical), macaque U6 (96% identical), rabbit U6 (73% identical), dog U6 (69% identical), guinea pig U6 (60% identical). Paralogues in human: RNU6-326P (81% identical), RNU6-429P (80% identical), RNU6-116P (79% identical), RNU6-1227P (79% identical), RNU6-140P (79% identical), RNU6-16P (79% identical), RNU6-658P (79% identical), RNU6-86P (79% identical), RNU6-1 (78% identical), RNU6-1075P (78% identical), RNU6-1085P (78% identical), RNU6-11P (78% identical), and 1284 more.